MTCO3P1 (MT-CO3 pseudogene 1)
Synonyms: U92032.1
Gene: Unprocessed pseudogene on chromosome 6 (32,706,124 to 32,706,955, reverse strand). Ensembl gene ENSG00000235040.
Diseases named in the same sentence as MTCO3P1 in open-access papers:
MTCO3P1 is named in the same sentence as 9 diseases in open-access papers, as found by Europe PMC text mining. Sharing a sentence is not in itself a finding about the gene and the disease. The quoted sentences say what the papers report.
alopecia areata (1 paper, 2023). Loss of scalp and body hair involving microscopically inflammatory patchy areas. "We also identified a novel association of rs3104394 in MTCO3P1 with alopecia areata reached experiment-wide significance only in AMR (PAFR=0.01,PAMR=1.27×10−11,PEUR=7.66×10−6)." (PMID 37425708, 2023).
Alzheimer disease (1 paper, 2021). A progressive, neurodegenerative disease characterized by loss of function and death of nerve cells in several areas of the brain leading to loss of cognitive function such as memory and language. "The MTCO3P1 genomic sequence might be involved haplotypically with Alzheimer’s disease and Alzheimer’s disease-related neuropathologies (National Institute on Aging Genetics of Alzheimer’s Disease Data Storage Site—Genomics database)." (PMID 34122517, 2021).
MTCO3P1 also shares sentences with these, for which no sentence is quoted: alopecia (1 paper); autoimmune Addison’s disease (1); Crohn disease (1); multiple sclerosis (1); narcolepsy (1); systemic lupus erythematosus (1); systemic sclerosis (1).